CYP2E1 (cytochrome P450 family 2 subfamily E member 1)
Diseases named in the same sentence as CYP2E1 in open-access papers (continued):
Sharing a sentence is not in itself a finding about the gene and the disease.
cancer (continued). "Several factors contribute to the alcohol mediated cancer initiation, including the actions of acetaldehyde, DNA methylation, induction of CYP2E1, and oxidative stress." (PMID 28805741, 2017). "For example, nitrosamine is a common procarcinogen that is metabolized by CYP2E1 into acetaldehyde, which can induce multiple cancer types." (PMID 27203676, 2016). "The genes COL9A3, INPP5A and CYP2E1 were found in the regions with most frequently occurring homozygous deletions in each of the groups of hyperplasias, benign and malignant tumours." (PMID 25955013, 2015). "A hospital-based study of CYP2E1*5B and CYP2E1*6 polymorphisms and gene-environment interactions in the risk of UADT cancers among Indians was conducted." (PMID 24151610, 2013). "It has been shown that CYP2E1 is one of the most active CYP450 isoforms in generating intracellular ROS and oxygen radicals are associated with cancer development and metastasis." (PMID 24207099, 2013). "Second, we only focused on five common polymorphisms, and is encouraged to examine more polymorphisms, especially the low-penetrance polymorphisms from other promising cancer-susceptibility genes, such as PTGS2 and CYP2E1 genes." (PMID 23874853, 2013). "As a result, people exposed to ABS do not have the risk of cancer formation and liver toxicity from chemicals metabolized by CYP2E1." (PMID 37476879, 2023). "Moreover, a previous study demonstrated that the inhibitory potential of CYP2E1 has the ability to boost the clearance of anti-cancer agents such as docetaxel and of the antiretroviral drug saquinavir." (PMID 37259384, 2023). "In particular, the cytochrome P450 2E1 (CYP2E1) activity is induced by chronic alcohol consumption, resulting in increased alcohol tolerance, oxidative stress and toxicity, with a consequently higher risk of developing cancer and liver injury." (PMID 35010587, 2021). "Also for CYP2E1, the associations between polymorphisms and UADT cancers lead to contradictory results." (PMID 29342885, 2018). "In addition, CYP1A2 and CYP2E1 were involved in the metabolic activation of various cancer ogenic substances and protoxins." (PMID 29534510, 2018). "Summarized ORs for CYP2E1 RsaI/PstI stratified by cancer type were also evaluated." (PMID 29156840, 2017). "The pooled result failed to identified any significant associations between CYP2E1 Dra I polymorphism and the urinary cancer risk (CD + CC vs. DD, OR = 0.913, 95% CI = 0.791–1.051, P = 0.202; C vs. D, OR = 0.978, 95% CI = 0.847–1.117, P = 0.748)." (PMID 29156840, 2017). "A series of genes (e.g. CYP1A2, CYP3A4, CYP19A1), related to cancer in Cytochrome P450 Family, were down-regulated, with the exception of CYP2E1, which was up-regulated and may be involved in carcinogenic process of cervical cancer." (PMID 28225065, 2017). "Still, previous reports on cancer-association in humans and the function of the encoded protein, at least for INPP5A and CYP2E1, propose that they may play a part in the CMT pathogenesis." (PMID 25955013, 2015). "CYP2E1 metabolizes ethanol and generates reactive oxygen species, and it has been suggested that it is important for the development of alcoholic liver disease and cancer, including hepatoblastoma and HNC." (PMID 24151610, 2013). "As for the PstI/RsaI polymorphism of CYP2E1, our result showed a significantly high cancer risk for the c2 homozygote in Asian populations, with no such association being found among Caucasian population under any of the three genetic models." (PMID 20969746, 2010). "In this field, numerous studies conducted on different populations and ethnic groups have indicated the absence of a major impact of the CYP2D6, CYP2C19 and CYP2E1 genes in cancer risk." (PMID 18423013, 2008). "To comprehensively investigate whether cancer transplantation affects liver zonation, we visualized the module scores of genes involved in distinct biological pathways according to the zonated expression of Alb and Cyp2e1." (PMID 36694005, 2023).
cancer (continued). "The underlying mechanisms of CYP2E1 dysregulation in cancers have not been fully elucidated." (PMID 34612013, 2021). "Indeed, links between CYP2E1 protein levels and cytokines activity have been shown in recent reports as well as variable CYP2E1 gene expression in numerous inflammatory diseases including cancer." (PMID 24207099, 2013). "In mouse hepatocytes and human hepatocyte-derived carcinoma cell (HuH) models, palmitate and lysophosphatidylcholine (LPC) increase the release of EVs, demonstrating the conservation of toxic-lipids and cytochrome P450 2E1 (CYP2E1) within serum EVs." (PMID 32466319, 2020). "These multiple rodent bioassays support a conclusion that styrene, via CYP2E1-mediated styrene oxide formation or ring-oxidized metabolite(s) from CYP2F metabolism, has a very low potential for inducing cancer in any tissue other than mouse lung." (PMID 28962520, 2017). "In these genetically modified mice, possible styrene metabolism by the human CYP2F isoform or that of native CYP2E1 in the CYP2F2-KO mice, also is insufficient to initiate any pre-neoplastic events resulting in potential cancer outcomes." (PMID 28962520, 2017). "Only CYP2E1 and CYP2W1 mRNA levels in cancer cases were significantly higher compared to normal matched samples (medians: 1.42 versus 1.29, P = 0.028, and 1.53 versus 0, P = 0.012, Wilcoxon rank-sum test, respectively)." (PMID 24699256, 2014). "After a careful full-text review of the remaining 22 studies, a further 13 articles were removed: 7 were reviews; 2 were not case–control studies; 2 focus on other SNPs of CYP2E1 or other cancer; and the rest 2 did not report sufficient data." (PMID 28074086, 2017). "Cytochrome P450 2E1 (CYP2E1), an ethanol-inducible enzyme, has been shown to metabolically activate various carcinogens, which is critical for the development and progression of cancers." (PMID 22957075, 2012). "Unlike CYP1B1 and CYP2E1—two other notable P450 enzymes that, while expressed in various cancers, including pediatric STSs, are also present in corresponding normal tissues—CYP2W1 appears to be exclusively upregulated in tumor tissues, making it a uniquely selective therapeutic target." (PMID 40136335, 2025). "CYP2E1 is the most abundant CYP isoform in human liver and is the main enzyme that metabolizes a number of low molecular weight compounds, such as ethanol, acetaminophen, benzene, and carbon tetrachloride, and cancer suspects like nitrosamines and azo compounds." (PMID 35509083, 2022). "Therefore, we speculate that the inhibitory effect of CYP2E1 on the Wnt/β-catenin pathway is ROS-dependent and downregulation of CYP2E1 is beneficial to HCC cells to cope with the ROS stress and favor cancer growth." (PMID 35509083, 2022). "Interestingly, effects of SO in the inhibition of cancer initiation were not proven by increased excretion through GST induction or decreased bioactivation by cytochrome P450 2E1 (CYP2E1) in liver homogenates." (PMID 32547652, 2020).
tumor (56 papers, 2012 to 2026). "TOP/FOPFlash reporter assay, western blotting, functional rescue experiments, Co-immunoprecipitation and reactive oxygen species detection were conducted to reveal the underlying mechanism of the tumor suppressive role of CYP2E1." (PMID 35509083, 2022). "Here, our results show that the expression of CYP2E1 is decreased in HCC tissues, and low expression of CYP2E1 is associated with larger tumor diameter, vascular invasion, tumor differentiation, and short survival time in patients with HCC." (PMID 35509083, 2022). "Therefore it is reasonable to speculate that decreased level of CYP2E1 may cause lower cytotoxicity and apoptotic rate, thus favoring tumor growth." (PMID 25238230, 2014). "Under conditions of chronic activation of Cyp2E1, chronic excessive increase in levels of reactive oxygen species and cell death, and subsequent dysregulated cell proliferation, lead to tumor formation (AO)." (PMID 40255499, 2025). "A xenograft tumor model in nude mice was used to examine the role of CYP2E1 in CA-induced hepatocellular carcinogenesis." (PMID 38844847, 2024). "We observed overall reduction in expression of Cyp2e1 in tumor tissues in comparison with normal livers but marked induction of Igf2, Afp, Dlk1, Epcam and Gpc3 in tumor areas." (PMID 37414763, 2023). "Q11, 1‐(4‐methyl‐5‐thialzolyl) ethenone, a newly developed specific inhibitor of CYP2E1 here remarkably attenuates tumor growth and prolongs survival in vivo." (PMID 37283464, 2023). "There are studies in the literature showing that CYP2E1 converts many xenobiotics such as nitrosamines, carbon tetrachloride, and benzene into mutagenic, electrophilic, and tumor-promoting metabolites." (PMID 37476879, 2023). "We verified that Cyp2e1 knockout can significantly inhibit tumor growth in a Lewis lung orthotopic xenograft model." (PMID 37875398, 2023). "Patients with larger tumor sizes (> 5 cm) or vascular invasion showed substantially reduced CYP2E1 expression compared with those with smaller tumor sizes (≤ 5 cm) (P = 0.049) or without vascular invasion (P = 0.046)." (PMID 35509083, 2022). "Downregulation of CYP2E1 protein was also confirmed by western blotting and IHC assays in 77.8% (28/36) and 75% (15/20) of the tumor tissues, respectively." (PMID 35509083, 2022). "CYP2E1 expression is down-regulated in HCC tissues, and this downregulation was associated with large tumor diameter, vascular invasion, poor differentiation, and shortened patient survival time." (PMID 35509083, 2022). "More strikingly, the expression level of CYP2E1 gradually decreased from well and moderately differentiated to poorly differentiated tumor tissues (P < 0.05)." (PMID 35509083, 2022). "CYP2E1 is the main P450 enzyme involved in ethanol metabolism, and its expression is also closely contacted with tumor diseases." (PMID 36313348, 2022). "The results show that CYP2E1 expression in the tumor tissues was markedly down-regulated compared with the adjacent nontumor tissues." (PMID 35509083, 2022). "We found a significant positive correlation between CYP2E1 expression and tumor‐killing immune cells." (PMID 34612013, 2021). "Increased expression of CYP2E1 in breast tumours correlated with more serious and invasive lobular types of tumours." (PMID 33809117, 2021). "Higher levels of CYP2E1 have been linked with the production of procarcinogenics, while upregulation of ITGA5 is known to be involved in higher invasiveness of tumor cells." (PMID 32078659, 2020). "The metabolism of ethanol by CYP2E1 and generation of ROS suggests a mechanism that can trigger genetic damage and/or maintain the tumor environment." (PMID 29362861, 2018). "CYP2E1 expression has been found to be both significantly lower in malignant breast tissue compared to normal tissue in humans and also lower in tumours of clinical stage I compared to stage II-IV." (PMID 25955013, 2015).
tumor (continued). "In contrast, CYP1B1 and CYP2E1 were most abundantly expressed and exhibited less inter-individual variability in both normal (mean Ct of 29.9 and 31.7, respectively) and tumor (mean Ct of 27 and 30.2, correspondingly) samples." (PMID 24699256, 2014). "In line with potential tumour-suppressing function of autophagy, we identified that the protein levels of the autophagy markers, followed the same pattern as that of CYP2E1 in MDA-MB-231 cells." (PMID 24207099, 2013). "We also recently reported that in the other CYP family, CYP2E1 immunoreactivity was markedly detected in hepatocytes around the tumor of MLC tissues compared to hepatocytes located in distant areas from the tumor in human liver." (PMID 23930207, 2013). "Considering the link between oxidative stress and tumor growth, it has been hypothesized that CYP2E1-mediated ROS generation could regulate breast carcinogenesis." (PMID 40723371, 2025). "However, with LNP-CTNNB1 treatment, tumor cells begin to express Cyp2f2, Arg1, and Ass1 along with diminished expression of Cyp2e1, Cyp1a2, Oat and others." (PMID 40442146, 2025). "However, with LNP-CTNNB1 treatment, tumor cells begin to express zone 1 markers, including Cyp2f2, Arg1, and Ass1, while decreasing expression of zone 3 genes (e.g., Cyp2e1, Cyp1a2, and Oat)." (PMID 39711542, 2024). "In addition, we demonstrated a positive correlation between the CYP2E1 enzyme activity and tumor weight." (PMID 37875398, 2023). "CYP2E1 activity is positively correlated with tumor weight in GBM rats." (PMID 37283464, 2023). "Notably, the correlation analysis showed that there was a positive correlation between CYP2E1 enzyme activity and tumor weight (r2 = 0.7031, P < 0.001)." (PMID 37875398, 2023). "As the downregulation of CYP2E1 occurred earlier than the onset of tumor occurrence, it was possible that decreased CYP2E1 might play a role in hepatocarcinogenesis." (PMID 35509083, 2022). "In addition, we found that smoking and drinking decreased the expression level of CYP2E1 in tumor tissues, respectively." (PMID 35509083, 2022). "In addition, several reports have proposed that CYP2E1 overexpression is cytotoxic to the tumor cells and inhibits rapid cell proliferation upon ethanol treatment." (PMID 35509083, 2022). "Furthermore, CYP2E1 is also closely related to the tumor immune microenvironment because its expression correlates strongly with the number of infiltrating monocytes and regulatory T cells (Treg)." (PMID 36313348, 2022). "Furthermore, CYP2E1 was involved in lipid metabolism and ferroptosis and related to the tumor immune microenvironment due to its strong correlation with the levels of infiltrating monocytes and Tregs." (PMID 34612013, 2021). "Because strong CYP2E1 expression drives tumour cells of the human liver into apoptosis, it seems likely that the increased expression of the enzyme in the cirrhotic liver and the associated production of ROS and carcinogens leads to an increased rate of malignant neoplasia." (PMID 33604316, 2021). "In addition, in tumor samples with mRNA data and CNV data, shallow deletion was significantly associated with downregulation of CYP2E1 mRNA (ANOVA p < 0.05)." (PMID 34612013, 2021). "The transformation of chemicals is important in carcinogenesis the Cyp450 families are key enzymes in tumor transformation, and mediate the metabolic activation of numerous pre-carcinogens, such as Cyp1a2 and Cyp2e1, which degrade xenobiotics, steroids and fatty acids." (PMID 32363190, 2020). "In GSE14520 dataset, we identified the fact that low expressions of four CYPs including CYP2A6, CYP2C8, CYP2E1, and CYP4A11 in tumor tissues were significantly associated with worse OS in HCC patients (log ranks P = 0.01, 0.006, 0.024, and 0.007, respectively)." (PMID 30148168, 2018).
tumor (continued). "Specifically CYP1B1 and CYP3A5 genes were significant upregulated in one tumor tissue (patients 4, and 7, respectively), while upregulation of CYP2E1 and CYP3A5 mRNAs were significant in 4 (patients 4, 5, 6 and 13), and 2 (patients 5 and 12) paired tumor samples, respectively." (PMID 24699256, 2014). "Several observations link CYP2E1 with inflammatory reactions and carcinogenesis in different tissues suggesting that CYP2E1 might be involved in the regulation of tumour growth." (PMID 24207099, 2013). "Given that CYP2E1 is one of the most active ROS-generating CYP450 isoforms and considering the link between oxidative stress and tumour growth we hypothesised that CYP2E1-mediated ROS generation could regulate breast carcinogenesis." (PMID 24207099, 2013). "In addition, ethanol is considered to be an inducer of P450 2E1 (CYP2E1), a co-carcinogen and/or tumor promoter." (PMID 23667679, 2013). "Recently, studies have demonstrated that CYP2E1 plays an important role in tumor progression, and may be used as a prognostic indicator." (PMID 22957075, 2012). "In addition, the tumor‐promoting effects of upregulating CYP2E1 in HMC‐3 were reversed by Q11." (PMID 37283464, 2023). "Specifically, ALB and CYP2E1 were highly expressed in normal areas, GPC3 and AKR1B10 were highly expressed in tumor areas, ACTA2 and COL1A1 were highly expressed in fibrostic areas, and PTPRC was highly expressed in inflammation areas." (PMID 40051627, 2025). "Conversely, CYP2E1 and ADH4 exhibited 3.1-fold (p=0.009) and 2.8-fold (p=0.013) decreases in tumor samples, confirming downregulation." (PMID 41164201, 2025). "The results showed that both the tumor tissue and the surrounding normal breast tissue expressed the enzymes CYP4B1 and others, such as CYP1B1, CYP2B6, CYP2C, CYP2D6, CYP2E1, and CYP11A1." (PMID 40723371, 2025). "Linoleic acid metabolism is mediated by cytochrome P450 (CYP1A2, CYP2C, CYP2J, CYP2E1, and CYP3A4) to proinflammatory and proangiogenic oxylipins resulting in tumor growth or metastasis." (PMID 35155234, 2022). "From liver lesion and cirrhosis to the tumor occurrence, in the rat HCC model of hepatocarcinogenesis the expression level of CYP2E1 gradually decreased with the aggravation of liver lesion." (PMID 35509083, 2022). "Ectopic expression of CYP2E1 inhibits cell proliferation, migration, invasion and EMT of HCC cells in vitro and inhibited tumor formation and lung metastasis in nude mice." (PMID 35509083, 2022). "Ectopic expression of CYP2E1 inhibits the proliferation, invasion and migration and epithelial-to-mesenchymal transition of HCC cells in vitro, and inhibits tumor formation and lung metastasis in nude mice." (PMID 35509083, 2022). "It appeared that APOC1 expressed at the highest level, followed by CYP2E1 and HPR in all tumor stages." (PMID 34081622, 2021). "Specifically, CYP2E1 is one of the most active ROS-generating CYP450 isoforms and it is considered the link between oxidative stress and tumor growth." (PMID 30611309, 2019). "Seven CYP450 genes including CYP1A2, CYP2A6, CYP2C8, CYP2C9, CYP2E1, CYP3A4, and CYP4A11 were downregulated in tumor tissues, which were validated in both GSE14520 and GSE36376." (PMID 30148168, 2018). "In our study, we found that several CYPs including CYP1A2, CYP2A6, CYP2C8, CYP2C9, CYP2E1, CYP3A4, and CYP4A11 were all downregulated in tumor tissues in HCC patients." (PMID 30148168, 2018). "In contrast, CYP2E1 mRNA was unequivocally expressed in all samples of the RMS tumor and paired non-tumor tissue from the same patients." (PMID 24699256, 2014). "Both CYP2E1 and CYP2W1 mRNA expression in the tumor samples were higher compared to normal matched samples between patients (P<0.02 and, P<0.01, respectively)." (PMID 24699256, 2014).